CD44 (CD44 molecule (IN blood group))
Diseases named in the same sentence as CD44 in open-access papers (continued):
Sharing a sentence is not in itself a finding about the gene and the disease.
tumor (continued). "DDX17 is also involved in the splicing of CD44, which is an extremely broad cell surface transmembrane glycoprotein and is mainly involved in the adhesion of tumor cells to host cells and the host matrix." (PMID 35992805, 2022). "CD44 is known to promote tumor formation through interactions with the tumor microenvironment and is involved in various cellular processes including invasion, proliferation and apoptosis in many types of cancer including GBM." (PMID 35682709, 2022). "In fact, platelets membrane (PM) expresses proteins such as D-selectin that recognize and interact with CD44-overexpressing circulating tumor cells (CTCs), which are strictly involved with tumor metastasis and angiogenesis." (PMID 36544135, 2022). "TIMP-1 expression was cytoplasmic within tumor cells, whereas CD44 was seen as positive staining of cytoplasmic membranes of tumor cells and within multiple cell types in the stroma." (PMID 36230997, 2022). "Using fresh retinoblastoma tissue, the co-expression of EpCAM and three other putative tumor stem cell markers CD44, CD24 and ABCG2 was examined." (PMID 36132125, 2022). "The soluble CD44 ectodomain has been demonstrated to compete with the CD44-HA interaction on malignant cells, inhibiting tumor progression and invasiveness." (PMID 35785191, 2022). "HA-NGs exhibited pH-dependent degradation and drug release in vitro, enhanced tumor killing efficacy, and excellent tumor homing capability due to hyaluronic acid and CD44 interaction." (PMID 35845404, 2022). "The risk of developing distant metastases based on histopathological characteristics (Ki-67, p16, Rb, OTP, CD44, and tumor diameter) was evaluated using multivariate regression analysis and the Kaplan–Meier method." (PMID 35805004, 2022). "Since CD44 is a multifunctional molecule, anti-CD44 agents have therapeutic potential in various tumor cells." (PMID 35456655, 2022). "In silico and in vitro analyses revealed that two established PCa tumor suppressor genes, CD44 and CDK12, represent targets for sdRNA-D19b and sdRNA-A24, respectively." (PMID 35455981, 2022). "Since the formation of CIC structures is essential for in-cell killing, we next explored the impacts of CD44 expression on tumor cell killing by NK cells." (PMID 35436988, 2022). "Mechanistically, miR-34a suppressed PCSC properties by inhibiting prostasphere formation, migration, and invasiveness of CD44+ PCa cells, as well as serial tumor transplantation." (PMID 36139695, 2022). "H4C4, a monoclonal antibody that recognizes the extracellular domain of CD44 (from residue 69 to residue 90), reduced tumor growth, metastasis, and post-radiation tumor recurrence in human pancreatic mice xenografts." (PMID 35785191, 2022). "Targeting CD44 turned out to be an effective way to enhance CICs formation, immune killing, and suppression of tumor growth." (PMID 35436988, 2022). "HA fragments can promote tumor cell growth through CD44-dependent tyrosine kinase signal in tumor cells." (PMID 35447719, 2022). "In particular, the CSC marker CD44 was positively associated with immune markers, such as CD163, indicating a role of M2 macrophages in tumour dedifferentiation, or CD3 and CD4, which are indicative of an immune response." (PMID 36358805, 2022). "CD44 is a transmembrane cell surface receptor that acts as a tumor initiating factor which PC has a high level in stem cell profiles and is an important therapeutic target." (PMID 37529006, 2022). "Pin1 also plays a crucial role in tumorigenesis mediated by CD44+CD133+ tumor-initiating Caco-2 cells." (PMID 35433695, 2022). "Since miR-24 is a CD44 target, and Tspan8 expression on the surface of some tumor cell cultures is mediated by CD44, we also suggested an indirect relationship between miR-24 and Tspan8 in OC progression." (PMID 36613908, 2022). "CD44, a transmembrane glycoprotein and an important biomarker of cancer stem cells (CSCs), is essential to many tumor cell activities, including proliferation and metastasis." (PMID 35172821, 2022).
tumor (continued). "And HA as the vital part of DBMN is a natural ligand of CD44, playing a key role in enriching T cells around tumor cells." (PMID 35672752, 2022). "The intracellular uptake of HA-drug conjugates was facilitated via CD44 caveolae-mediated endocytosis on tumor cells, thus enhancing the targeted drug delivery efficiency." (PMID 35267773, 2022). "A cluster of CD44 acts as a tumor promoter by playing a role as a platform in the effective presentation of growth factors to their receptors especially for receptor tyrosine kinases." (PMID 35328667, 2022). "The proportion and number of both CD44− CD62L+ naive and CD44+ CD62L+ Tcm CD8 T cells decreased over time in the tumor." (PMID 35472220, 2022). "Abundant studies have demonstrated that CD44 serves as a marker for several tumour stem cells, including CSC-Gs." (PMID 36316684, 2022). "Expression profiles of MIF, CXCL12, and the receptors CXCR4, CXCR2, CXCR7, CD74, and CD44 were first analyzed using an RNA sequencing (RNA-seq) dataset (GSE62564) of 498 primary NB tumor samples." (PMID 35715791, 2022). "In cancer in general, CD44 is regarded as a tumor promoting protein, acting through, amongst others, interactions with HA and the PI3K-AKT pathway." (PMID 35267625, 2022). "Since the discovery of CSCs, CD44 has evolved as useful marker for detection and isolation of this particular tumor cell subset." (PMID 35215208, 2022). "CD44-mediated signaling has been implicated in MMP-mediated matrix degradation, tumor growth, and tumor invasion." (PMID 35204054, 2022). "Further in-depth study of each signaling pathway verified that monocytes were directly associated with tumor cells only in the MIF and TNF pathways, in which the most important ligand-receptors were CD74/CD44 and TNF/TNFRSF1B." (PMID 36479092, 2022). "The ZCPH exhibited precise targeting to specific marker CD44 on the tumor cell and satisfied dose-dependent toxicity toward SKOV3 cells." (PMID 36500444, 2022). "Blood lakes were found in most EWS tumor samples, and these tumor cells expressed CD44, TFPI-1 and EphA2." (PMID 35354905, 2022). "Taken together, these results suggest that Pin1 activity is essential for CD44+CD133+ tumor-initiating Caco-2 cell-induced tumorigenesis in vivo, and that Juglone or KPT6566 effectively inhibit tumor-initiating Caco-2 cell-mediated tumor growth." (PMID 35433695, 2022). "In summary, our study revealed that among the investigated markers only CD44 expression was positively correlated with advanced tumor stage, but exclusively in the group of pRCCs." (PMID 36079127, 2022). "CD8+ T cells in the lung of 4TO7-Lin28B tumor-bearing host included a smaller CD44+CD62L− T cell population and expressed lower CTLA-4 and granzyme B." (PMID 35173168, 2022). "CD44 isoforms, including CD44H, CD44v6, or CD44v9, detected in humans were linked to tumor differentiation status." (PMID 35457063, 2022). "Based on the unique pH and redox environment of tumor tissues, the objective of the authors was to obtain NPs with pH- and redox-responsive release capable of CD44 targeting." (PMID 36297526, 2022). "We evaluated DOX-NP cytotoxicity, the effect on the cell cycle and on the expression of CD44 antigen, a molecule involved in adhesion and in tumor invasion, comparing DOX-NP to free DOX and stand-alone SiNPs." (PMID 35328491, 2022). "CD44 is one of the key components determining the tumor-endothelial interaction and tumor-stromal interactions." (PMID 35328667, 2022). "The dot plots showed the proportion of cells expressing tumor stemness-related gene markers (CD44 and MKI67) and key DEeRNAs (PHLDA1 and RASD1) and their scaled relative expression level in 12 cell clusters." (PMID 36092920, 2022). "Specifically, they showed that tumour-associated macrophages influenced CD44 expression and mediated stemness via the PI3K-4EBP1-SOX2 pathway; further, a CD44 isoform switch regulated EMT plasticity." (PMID 34831291, 2021).
tumor (continued). "In this study, we used an Ab that cross-reacts with both human and mouse origin CD44 of all isoforms to unveil the type of leukocyte responsible for high splenic anti-CD44 uptake and investigate how its regulation can influence tumor immuno-PET." (PMID 33594192, 2021). "Accumulating data show that CD44 promotes tumor progression via regulating proliferation and EMT process." (PMID 33661757, 2021). "The protein expression of PRDX2 was remarkably higher and frequently upregulated in CD133(+)/CD44(+) tumor tissues compared to CD133 (-)/CD44(-) tumor tissues." (PMID 33819194, 2021). "Administering 89Zr-anti-CD44 with a total Ab dose of 700 μg further reduced splenic uptake half-fold and augmented tumor uptake two-fold." (PMID 33594192, 2021). "With respect to tumor grade, it was found that CD44 expression had extreme elevation in grade III (75.03 ± 4.17) compared to grade II (61.16 ± 7.7, p < 0.0001) and grade I (54.4 ± 6.06, p = 0.002)." (PMID 34837915, 2021). "The results revealed that administering 89Zr-anti-CD44 with a total Ab dose of 300 μg indeed reduced the level of splenic uptake and improved tumor uptake compared to when 100 μg was administered." (PMID 33594192, 2021). "We further investigated if miR-30c regulates tumor cell cluster formation and if miR-30c has any regulatory effects on CD44 and EGFR levels." (PMID 33995681, 2021). "The importance of this fact lies in the relationship between the EMT process and stemness, since it has been confirmed that cancer cells subjected to EMT develop stemness markers such as high CD44 expression and increased ability to form tumor spheres." (PMID 34503571, 2021). "This allows an increase in the uptake of the active compounds into the tumor mass overexpressing certain receptors of the polysaccharide, such as the cluster determinant 44 (CD44) and the receptor for hyaluronate-mediated motility (RHAMM)." (PMID 33804970, 2021). "PRDX2 expression was remarkably higher and more frequently upregulated in CD133(+)/CD44(+) tumor tissues compared to CD133(-)/CD44(-) tumor tissues." (PMID 33819194, 2021). "Hou and collaborators showed that the CD133+CD44/high pattern identifies the fraction of tumor cells responsible for hematogenous metastasis in HCC." (PMID 34572776, 2021). "They reported that downregulation of CD44, a marker for breast CSCs, is involved in inhibiting tumor stem cell self-renewal and increases the sensitivity of stem cells to RT and chemotherapy." (PMID 34500557, 2021). "Based on the hyaluronic acid coating, TPL/NPs exhibited selective tumor cellular uptake and high tumor tissue accumulation capacity by targeting CD44." (PMID 34162396, 2021). "GSCs can be isolated in a patient’s tumor using single surface markers including cluster of differentiation 44 (CD44) among others." (PMID 33671112, 2021). "Our previous studies demonstrated that homophilic CD44 interactions mediate tumor stem-cell aggregation and polyclonal metastasis." (PMID 34067416, 2021). "The independent inhibition of hyaluronan-producing cells, hyaluronan synthesis, and/or CD44 expression, has been found to decrease the tumor cell’s proliferation, motility, invasion, and metastatic abilities." (PMID 33921242, 2021). "Loss of another miRNA, miR-34, has been detected in CD44 + /CD133 + tumorsphere-forming and tumor-initiating PCSCs, accompanied with increased levels of Notch/Bcl-2." (PMID 34453639, 2021). "Another potential target for DMG tumours that has recently been explored is the transmembrane receptor CD44." (PMID 34944870, 2021). "Immunoprecipitation revealed that Hsp90ab1 and Eno1 interact and inhibit the progression of tumor cells by blocking TGFβ activation and interacting with CD44, a cell-adhesion receptor." (PMID 34830748, 2021). "The high expression of CD44 in hypoxic tumor regions is plausible because hypoxia promotes CXCR4-mediated cell homing 42-44." (PMID 34093792, 2021).
tumor (continued). "In the present study, patients with R‐type tumors expressing high CD44 in the tumor periphery of GBM showed the shortest survival time after Bev therapy, and the primary tumor showed a much more invasive type on MRI compared with patients with S‐type tumors." (PMID 33543833, 2021). "CD44 functions in supporting tumour progression and aggressiveness can be attributed to its diverse binding ligands and interactome." (PMID 34944493, 2021). "CD44 regulates the growth, migration, and invasion characteristic of CSCs in addition to modifying the extracellular matrix of tissues to support new tumor formation." (PMID 34884848, 2021). "We are currently investigating how and why CD44+CD133+ tumor-initiating Caco-2 cells isolated from primary xenografts form tumors faster than parental Caco-2 cells." (PMID 33994850, 2021). "Other potentially active biological tumor markers predicting resistance to NCRT are cluster of differentiation 44 (CD44) and the Hedgehog pathway markers receptor protein patched homolog 1 (PTCH1) and ligand Sonic Hedgehog (SHH)." (PMID 33151397, 2021). "Another tumor-specific targeting moiety is hyaluronic acid (HA), which binds to CD44, a cell adhesion membrane glycoprotein that is overexpressed on metastatic breast cancer cells." (PMID 33672261, 2021). "To identify the HA receptor that mediates binding of tumor cells to bmMSCs in our experimental setup, we next silenced the HA receptor genes CD44, RHAMM and LAYN by siRNA." (PMID 34707175, 2021). "Several tumor cells overexpress CD44, and it has been related to tumor progression, apoptosis evasion, and multidrug resistance." (PMID 33744285, 2021). "The macrophage-secreted OPN in the tumour microenvironment binds to CD44 expressed by the tumour cells, which subsequently promotes clonal growth, invasion and metastasis." (PMID 34944493, 2021). "The key role of CD44 in maintaining the cancer stemness of BCa cells is inseparable from tumor growth, distant metastasis, and drug resistance." (PMID 33573671, 2021). "The conjugation of SLM to PEGylated Au NPs improved the drug uptake by breast CSCs expressing CD24−/CD44+ markers and enhanced drug-induced tumor cell death." (PMID 34361141, 2021). "The results of this study demonstrate that CD44+CD133+ Caco-2 cells have characteristics of tumor-initiating cells." (PMID 33994850, 2021). "Tumor cells escape immune surveillance through CD44-dependent upregulation of programmed death ligand 1 (PD-L1)." (PMID 34063134, 2021). "GBMs expressing CD44 at a much higher level in the tumor periphery than in the tumor core (high P/C ratio of CD44) were refractory to Bev therapy, and patients showed much shorter survival than when their tumors expressed a low P/C ratio of CD44." (PMID 33543833, 2021). "In this case, the CD44+ TEVs released by the tumor cells of the HeyA8 ovarian cell line were able to transfer this receptor onto the human peritoneal mesothelial (HPMCs) cells." (PMID 33540535, 2021). "It has been reported that CD44 is one of the biomarkers and a key regulator of cancer stem cells (CSCs), including self-renewal, tumor initiation, and metastasis." (PMID 34744733, 2021). "We found that LGALS9_CD44, MIF_TNFRSF14, CD47_SIRPG, MDK_LRP1 and LGALS9_HAVCR2, CD74_COPA, C3_C3AR1, ANXA1_FPR3 interactions were upregulated in both ductal-tumor and malignant cells versus ductal-normal." (PMID 35087839, 2021). "During the pathologic process of skin, CD44 is expressed on keratinocytes membranes and the infiltrating lymphocytes near the inflammation localization or tumor localization." (PMID 34361560, 2021). "Our results demonstrated that PRDX2 knockdown inhibits the self-renewal capacity of CD133+CD44+ CCSCs in vitro and the tumor incidence and growth of these cells in vivo." (PMID 33819194, 2021). "For example, Moesin (MSN) activates tumor progression by interacting with CD44 to induce Wnt/b-catenin pathway proliferation." (PMID 34512630, 2021).
tumor (continued). "Recent studies indicate that CD44 variants are restricted to CIC populations and promote tumor development in animals." (PMID 33451103, 2021). "CD44, a marker of cancer stem cells, has also been shown to regulate iron homeostasis and modulate iron entry into tumor cells." (PMID 34370716, 2021). "Next, we compared the DEGs between CD44+ tumor cells and CD44- tumor cells, and the enrichment analysis results verified the immunity function of CD44." (PMID 35187044, 2021). "HER2 and CD44 were the only significant biological tumor markers at univariable logistic regression analysis (LRT p value = 0.043 and LRT p value = 0.051) and were therefore considered for further analysis." (PMID 33151397, 2021). "Ostensibly, as CD44 is overexpressed in a variety of cancer types and is a recognised marker of cancer stem cells, this mode of internalisation should allow facile tumour identification." (PMID 34234213, 2021). "CD44 marker participates in multiple physiological processes and its aberrant expression and dysregulation contributes to tumor initiation and progression." (PMID 34837915, 2021). "For all these reasons, we have selected HA as a ligand to target 4T1 tumor cells that overexpress CD44." (PMID 34867360, 2021). "A large number of studies have shown that CD44 is related to tumor metastasis, invasion and prognosis." (PMID 34150667, 2021). "Tumors from MUP-uPA mice fed the HFHC diet exhibited an increased expression of tumor markers Ly6d, Cd44, Golm1, and Birc5, as well as higher levels of the proliferation marker Mki67." (PMID 34439245, 2021). "Combined treatment of AA-TNBC-derived tumors with GANT61, DAPT, and doxorubicin/carboplatin results in significant tumor regression, and tumor-dissociated cells show mitigated migration, invasion, mammosphere formation, and CD44+/CD24- population." (PMID 34889737, 2021). "These experimental differences suggest that CD44 can be oncogenic or tumor suppressive depending upon the host immune microenvironment." (PMID 34827550, 2021). "It was shown that human tumor cell lines overexpress the HA receptor (CD44), which enhances the uptake of the nanovectors through receptor-mediated endocytosis." (PMID 34209588, 2021). "Knocking down XBP1, CXCR4, and CD44 by siRNA technology altered the interplay between tumor cells and HBMECs." (PMID 34093792, 2021). "Meanwhile, the CXCR4 and CD44 expression was significantly upregulated in DLBCL tumor cells under hypoxic condition." (PMID 34093792, 2021). "Previous studies have demonstrated that the Onco-P20 conjugate interacts with CD44, enters cells through a receptor-mediated mechanism, and exerts a concentration-dependent inhibitory effect on tumor cells." (PMID 34073987, 2021). "Total RNA and protein of the mouse tumor tissues were extracted, and the expression of CD44, EpCAM, and MKL-1 was detected by RT-PCR and Western Blot, respectively." (PMID 34239355, 2021). "CD44-HA constitutes a molecular tandem that can affect tumor immunology by utilizing complex mechanisms." (PMID 33800172, 2021). "Although a direct role for Wnt/β-catenin pathway upregulation in maintaining the tumor-initiating properties of CD44+CD133+ Caco-2 cells needs to be confirmed, our results suggest that this is plausible." (PMID 33994850, 2021). "We established tumor-targeting NPs, combining FD binding to P-selectin-expressing tumors and TH targeting CD44-expressing tumors to reduce P-gp expression." (PMID 34575403, 2021). "Considering the expression of CSC-related genes CD44 and CD133 (PROM1) the CD44+ sorted cells demonstrated increased expression than the mixed population of OSCC tumor cells." (PMID 34205649, 2021). "The CD44 expression was positively correlated with tumor stage (r = 0.656), tumor grade (r = 0.645), and the proliferative activity of DNA cell cycle (S phase, r = 0.396)." (PMID 34837915, 2021). "PCSCs with high tumor-initiating and metastatic capacities are enriched in the side population, CD44+, and CD44+α2β1+ subpopulations." (PMID 33763422, 2021).